ENSG00000187951 (novel transcript)
Synonyms: LOC100288637
Gene: Long non-coding RNA gene on chromosome 15 (30,658,717 to 30,772,993, forward strand). Ensembl gene ENSG00000187951.
Gene Ontology:
Biological process: miRNA-mediated post-transcriptional gene silencing